MSX1 (msh homeobox 1)
Diseases named in the same sentence as MSX1 in open-access papers (continued):
Sharing a sentence is not in itself a finding about the gene and the disease.
retinoblastoma (1 paper, 2022). A malignant tumor that originates in the nuclear layer of the retina. "In addition, retinoblastoma showed moderate expression of MSX1, which was highest in tumor tissue and lowest in the choroid." (PMID 36012688, 2022). "The expression patterns of MSX1 and MSX2 were similar in 8-week human embryo and retinoblastoma, whereas both were absent in postnatal human eye." (PMID 36012688, 2022). "MSX1 and MSX2 expression was similar in the developing eye and retinoblastoma, whereas it was absent in the postnatal eye." (PMID 36012688, 2022).
Rieger syndrome (1 paper, 2022). "In humans, MSX1 is also restricted to the dental mesenchyme as in mice and is a crucial player in human odontogenesis as evidenced by the fact that mutation in MSX1 results in Rieger syndrome, which exhibits severe tooth agenesis." (PMID 35211032, 2022).
serous ovarian cancer (1 paper, 2020). "Cellular experiments validated hypomethylation of CpG sites within the MSX1 gene highly associated with resistant high-grade serous ovarian cancer (HGSOC) disease at presentation and identified expression of MSX1 as conferring platinum drug sensitivity." (PMID 32322170, 2020).
ventricular septal defect (1 paper, 2018). The presence of a defect (opening) in the septum that separates the two ventricles of the heart. "In a previous study, we found that variants in the MSX1 gene are closely associated with the risk of ventricular septal defect (VSD, a common type of CHD)." (PMID 29423089, 2018).
tumor (40 papers, 2006 to 2026). "Epigenetic silencing of MSX1 through DNA methylation can lead to different phenotypes or even increase the risk for tumor growth." (PMID 38523193, 2024). "High MSX1 activity is associated with the inhibition of migration and proliferation in different tumor types." (PMID 35011618, 2021). "The analysis confirmed a (moderate) increase in the expression of Ascl2 and other Wnt target genes Axin2, Lgr5, and SP5 in Apc/Msx−double-deficient tumor cells when compared to the cells with intact Msx1 gene." (PMID 30733598, 2019). "Tumor samples from high-risk group A showed a higher mean overall IHC score for Anti-MSX1, Anti-CD271, Anti-ERRFI1, Anti-PTPRF, Anti-TNFRSF21, Anti-TNFRSF12a, and Anti-IGFBP2, but without significance." (PMID 30641895, 2019). "Only one potential germline variant, MSX1 (chr4: 4,861,985 T > G, c.359T > G, p.V120G, NM_002448), showed loss of the wild type allele in both the tumor DNA of family members II.1 and II." (PMID 29134539, 2018). "Indeed, the enhanced glial progenitor-like profiles including Rspo1, Zfp423, and Msx1 were significantly reduced, whereas Otx2 mRNA levels remained unaltered in Sox2-deficient tumor cells." (PMID 40128799, 2025). "The homeodomain of MSX1 stimulates apoptosis of cancer cells, which might offer a role for the MSX1, as an indicator of tumor susceptibility." (PMID 36672972, 2023). "However, expression of only one gene, encoding serine/threonine kinase 32B (Stk32b), differed significantly between Msx1 wt and Msx1-deficient tumor tissue." (PMID 30733598, 2019). "Since MSX1 has been identified as both a tumor suppressor and an oncogene in tumorigenesis, but its function in CC remains elusive to date, the present study aims to elucidate the role of MSX1 in CC and its precancerous stages." (PMID 42248834, 2026). "We identified cohort-specific DNA methylation markers in the CpG islands of PDX1, EN2, and MSX1 and validated tumor-specific hypermethylation levels of these three genes via optimized qMSP methods with highly sensitive primer sets." (PMID 35169223, 2022). "Patients with an MSX1-expression in more than 10% of tumor cells had a significant longer survival compared to those without this expression-pattern." (PMID 32630554, 2020). "The lowest p-value can be found for the variable “MSX1 > 10%” (MSX1-expression in more than 10% of tumor cells) (p = 0.066) with a hazard ratio of 0.147." (PMID 32630554, 2020). "A significant better survival over the whole study cohort was found in those cases, with more than 10% of the tumor cells that are showing a positive staining for MSX1 (p = 0.023)." (PMID 32630554, 2020). "The tumor status (t-status) showed significant differences for the MSX1-staining in T1, T2, and T3 tumors (p = 0.03)." (PMID 32630554, 2020). "In summary, our findings demonstrate for the first time that homeoprotein Msx1 is a novel negative regulator of tumor angiogenesis." (PMID 32784646, 2020). "To explore the role of homeobox protein Msx1 on tumor angiogenesis, which is essential for tumor growth, we examined the effects on VEGF-induced proliferation, migration, invasion, and tube formation in human endothelial cells." (PMID 32784646, 2020). "Although the MSX1 role in human CRC has not yet been described, several studies identified MSX1 promoter hypermethylation in CRC, suggesting MSX1 downregulation in tumor tissue." (PMID 30733598, 2019).
tumor (continued). "MSX1 (ENSG00000163132) encodes a member of the muscle segment homeobox gene family, and the overexpression of MXS1 can inhibit the proliferation of tumor cells." (PMID 31660264, 2019). "In contrast, we observed increased expression levels of MSX1 in the majority of intestinal neoplasia, implicating a broader role of MSX1 in tumor initiation and/or progression." (PMID 30733598, 2019). "Accordingly, MSX1 operates as a tumor suppressor in NK-cells and as an oncogene in T-cell progenitors." (PMID 29746601, 2018). "On the other hand, four genes (ANKRD11, PHLDA3, APOL1 and MSX1) are known as tumour-suppressor factors." (PMID 19826427, 2009). "MSX1, a homeobox gene important for embryonic neural crest development, can induce the inhibition of tumour-initiating ability in soft agar in vitro." (PMID 19826427, 2009). "Mechanistically, RNA sequencing results suggest LCFAs may primarily suppress tumor progression through the transcriptional regulation of MSX1, CEBPG, and NR2F2." (PMID 41614948, 2026). "Our results demonstrate that MSX1 acts as a tumor-promoting factor in CC." (PMID 42248834, 2026). "MSX1 is a protein, that as a transcriptional repressor plays a role during embryogenesis (especially during the formation of limb-patterns, craniofacial development, odontogenesis), but also is thought to function in tumor growth inhibition." (PMID 37101223, 2023). "By examining the differences in the methylation levels observed in tumors and adjacent healthy tissues via hybrid capture-based targeted bisulfite sequencing, we discovered significantly hypermethylated intragenic CGI regions in PDX1, EN2, and MSX1 in the tumor samples." (PMID 35169223, 2022). "Furthermore, in the tumor masses arising in TG mice, we detected the downregulation of LAMC2 and MSX1 (laminin subunit gamma 2- and MSH homeobox 1-encoding genes, respectively), which are also downregulated in human poorly differentiated EC24." (PMID 33893331, 2021). "Thus, HHEX is the second identified NKL homeobox gene after MSX1 representing a tumor suppressor as well as an oncogene." (PMID 32922661, 2020). "In our previous experiments, we found a dramatic reduction in tumor size by Msx1 overexpression." (PMID 32784646, 2020). "Injection of Ad-Msx1 suppressed the tumor growth significantly by measuring the tumor weight." (PMID 32784646, 2020). "We have shown that Msx1 inhibits tumor growth by inducing apoptosis in cervical cancer." (PMID 32784646, 2020). "Our results showed that Msx1 can exert its tumor suppressive effect by inducing apoptosis." (PMID 32784646, 2020). "We hypothesized that the inhibition of tumor growth by Msx1 might be due to the inhibition of angiogenesis." (PMID 32784646, 2020). "Thus, we thought that the possibility of a novel function of Msx1 in the inhibition of tumor growth would involve regulation of angiogenesis and initiated the function of Msx1 in angiogenesis." (PMID 32784646, 2020). "However, Msx1 can exert its tumor suppressive effect through the inhibition of angiogenesis since growth of the tumor relies on sufficient blood supply from the existing vessels to provide oxygen and nutrients for tumor growth." (PMID 32784646, 2020). "Furthermore, analysis of human tumor specimens showed that MSX1 is upregulated in various progression stages of intestinal neoplasia." (PMID 30733598, 2019). "In particular, BNC1 and MSX1 were highly sensitive and specific for tumor detection." (PMID 17194184, 2006). "However, Msx1 can exert its tumor suppressive effect by inhibiting angiogenesis." (PMID 32784646, 2020). "Therefore, it is tempting to speculate that in CRC, MSX1 represents a tumor-promoting gene with some essential function." (PMID 30733598, 2019).
tumor (continued). "Moreover, in this cancer MSX1 acts as a tumor suppressor, suggesting that the expression of MSX1 might be more generally regulated by this pathway." (PMID 31143370, 2019). "In conclusion, a germline variant in MSX1 was identified in the normal DNA of three affected members of a family with clustering of BE and EAC, in addition the investigated tumors showed somatic loss of the wild type allele, consistent with biallelic inactivation of a tumor suppressor gene." (PMID 29134539, 2018). "Several additional genes—including FSTL1, LRPAP1, MSX1, and APP—exhibited distinct immune interaction profiles, suggesting diverse roles in modulating tumor–immune dynamics." (PMID 40943183, 2025). "Compared to normal samples, the expression of E2F2, FOXJ1, EMX1, PAX7, NKX6-1, FOXD1, and ZNF552 was significantly higher (P < 0.05) and the expression of MSX1, STAT4, NR3C2, and EGR3 was significantly lower in tumor samples (all P < 0.05)." (PMID 33688372, 2021). "The corresponding genes of these three DMPs were mesothelin (MSLN), protein kinase cAMP-dependent type II regulatory subunit beta (PRKAR2B), and msh homeobox 1 (MSX1), all of which correlated with tumor development, malignancy, and treatment." (PMID 33995018, 2021). "Some of the top DNA hypermethylated IRGs, such as BMP8B, PLA2R1, MSX1, DGCR5, and MT1G, were previously identified as tumor suppressors in gastric and other cancers." (PMID 32841292, 2020). "Further investigations are needed in order to display an increasing development of MSX1 and TWIST expression during tumor progression." (PMID 30641895, 2019). "In vitro studies using non-colonic cell lines have indicated that miR-148a exerts a tumor suppressive function by targeting several genes such as PXR, TGIF2, MSX1, CDC25B, DNMT1 and DNMT3b." (PMID 23056401, 2012). "Since MSX1 advances the invasive phenotype due to EMT, the upregulation of this gene could be beneficial in tumor progression." (PMID 35486660, 2022). "The lack of apparent Gdf7 and Msx1 expression in the Math1+ tumor tissue of Gdf7Cre/+;SmoM2 mice argues against this possibility." (PMID 22539980, 2012). "However, the function of Msx1 in tumor angiogenesis has not been reported." (PMID 32784646, 2020).
cancer (24 papers, 2009 to 2026). A tumor composed of atypical neoplastic, often pleomorphic cells that invade other tissues. "MSX1 takes role in infamous metastatic step called Epithelial Mesenchymal Transition (EMT) which is also defined as a cancer hallmark." (PMID 35486660, 2022). "Some of the significant cancer hallmark terms are epithelial-mesenchymal transition (MSX1, CXCL12, SCG2, SLIT2), KRAS signaling up (F13A1, ADAMDEC1), inflammatory response (CCL5, VIP), IL-6/JAK/STAT3 signaling (CXCL13)." (PMID 35486660, 2022). "The found positive correlation between MSX1 and progesterone receptors A and B confirms the results of a previous study on cancer tissue by our research group." (PMID 37101223, 2023). "We were also able to confirm the positive correlation between MSX1 and progesterone receptors A and B found in a previous study on cancer tissue by our research group." (PMID 37101223, 2023). "Our results suggest that the homeoprotein Msx1 can be a potential therapeutic target for angiogenesis inhibition in pathological conditions including cancers." (PMID 32784646, 2020). "Our previous report characterized Msx1 as a potential repressor of cell cycle progression, as evidenced by a marked increase in the length of the G1 phase of the cell cycle in cancer cells." (PMID 32784646, 2020). "Therefore, we were able to confirm the results of our former paper on cancer tissue, where a significant positive correlation between MSX1 and the progesterone-receptors A and B was also found." (PMID 37101223, 2023). "Interestingly, during the tooth, facial, limb, and neuronal development, or in human carcinoma cells, Msx1 expression is regulated by bone morphogenetic protein (BMP) signaling." (PMID 30733598, 2019). "Methylation of PAX9 and MSX1 have been associated with cancer development but have not been described the relation between this phenomenon and dental agenesis." (PMID 24316698, 2014). "Mechanistic insights revealed an MSX1-dependent induction of the epithelial-to-mesenchymal transition (EMT), a process highly correlated with cancer development and progression." (PMID 42248834, 2026). "Interestingly, mutations in the AXIN2, MSX1, PAX9, and WNT10A genes may be associated with cancers." (PMID 34378652, 2021). "The misexpression of homeobox transcription factor genes has also been reported in cancer tissues; for example, HOXA1 and Six1 transform mammary epithelial cells, and Msx1 and Cdx transform myoblasts and intestinal epithelial cells, respectively." (PMID 21600039, 2011). "They identified several genes (AXIN2, MSX1, PAX9, WNT10A, EDA, BARX, and BRCA1) that may play a role in both hypodontia and cancer development." (PMID 38523193, 2024). "Interestingly, AQP4_Astrocytes cluster derived from EPN highly expressed some anti-cancer genes, such as JUN, IRF1 and MSX1." (PMID 38383423, 2024). "In the MCF7 epithelial carcinoma cell line, Kcnk5b induced ALDH1a2, PEA3, and MSX1." (PMID 33830014, 2021).
infection (6 papers, 2011 to 2024). The state of being infected such as from the introduction of a foreign agent such as serum, vaccine, antigenic substance or organism. "MSX1, whose overexpression in mouse neurospheres promotes oligodendrogenesis, is overexpressed at day 3 post-infection (p.i.)at both MOIs." (PMID 38478163, 2024).
MSX1 also shares sentences with these, for which no sentence is quoted: Hypodontia (24 papers); multiple myeloma (2); splenic marginal zone lymphoma (2); T-cell acute lymphoblastic leukemia (2); van der Woude syndrome (2); basal cell nevus syndrome (1); blepharocheilodontic syndrome (1); cervical tumor (1); clear cell renal cell carcinoma (1); cleft lip and palate (1); colitis (1); dental anomalies (1); developmental delay (1); Down syndrome (1); E. coli infection (1); endometrioid ovarian carcinomas (1); endometriosis (1); Floating-Harbor syndrome (1); genetic disorders (1); glioma (1); gynecological tumors (1); incontinentia pigmenti (1); infectious colitis (1); lip (1); lung diseases (1); lung squamous cell carcinomas (1); lymphoid leukemia (1); MALT lymphoma (1); marginal zone B-cell lymphoma (1); Microdontia (1).
A further 14 diseases each share a sentence with MSX1 in 1 paper.